TNC (tenascin C)
Diseases named in the same sentence as TNC in open-access papers (continued):
Sharing a sentence is not in itself a finding about the gene and the disease.
lymph node metastasis (8 papers, 2015 to 2023). "Tenascin-C expression in stromal fibroblasts was associated with patient’s age (p = 0.018), pT stage (p < 0.001), lymph node metastasis (p = 0.002), clinical stage (p = 0.002), and cancer recurrence (p < 0.001)." (PMID 26731558, 2016). "In addition, Tenascin-C expression is associated with lymph node metastasis in breast, colon, liver, and oral squamous cell carcinoma." (PMID 26731558, 2016). "In addition, we demonstrated that TNC upregulation was associated with lymph node metastasis." (PMID 27191989, 2016). "The expression of both TNC and Paxillin were increased in tissues of squamous cell carcinoma with lymph node metastasis." (PMID 29088796, 2017). "Lymph node metastasis occurred most frequently in Tenascin-C positive in both stroma and cancer cells, followed by Tenascin-C positive in either of stroma and cancer cells and Tenascin-C neative in both stroma and cancer cells." (PMID 26731558, 2016). "Tenascin-C expression in ESCC stromal fibroblasts was associated with patient’s age, tumor (pT) stage, lymph node metastasis, clinical stage, and cancer recurrence." (PMID 26731558, 2016). "Moreover, TNC expression status and lymph node metastasis were independent prognostic factors for poor OS among the TNBC patients in multivariate Cox regression analyses." (PMID 32732922, 2020). "In the present study, we also found that Tenascin-C expression in ESCC stromal fibroblasts was related to pT stage, lymph node metastasis, clinical stage, and cancer recurrence." (PMID 26731558, 2016). "In lymph node metastasis-positive group, the 5-year OS and DFS rates of the Tenascin-C-positive group (positive expression in stroma and cancer, respectively) were also significantly lower than those of the Tenascin-C-negative group (in addition to OS rate of the stroma-Tenascin-C- positive group)." (PMID 26731558, 2016). "Furthermore, the 5-year OS and DFS rates of the Tenascin-C-positive group (positive expression in stroma and cancer, respectively) were significantly lower than those of the Tenascin-C-negative group in lymph node metastasis-negative group." (PMID 26731558, 2016). "Finally, we performed a LASSO logistic regression analysis of the gene expression matrix of seven of the THCA cohort from the TCGA database by the presence or absence of lymph node metastasis to finalize the risk scores constructed for the five most relevant genes (EVA1A, SERPINA1, FN1, TNC, MXRA8)." (PMID 35141140, 2021).
non-small cell lung carcinoma (8 papers, 2008 to 2022). A group of at least three distinct histological types of lung cancer, including non-small cell squamous cell carcinoma, adenocarcinoma, and large cell carcinoma. "This study was conducted to evaluate the potential significance of Tenascin-C as a predictive marker for tumor progression in the sera of non-small cell lung cancer (NSCLC) patients." (PMID 26967391, 2016). "Some studies showed that the large isoform of Tenascin-C was overexpressed in non-small cell lung cancer that showed recurrence, suggesting that Tenascin-C is crucial for the progression and spread of cancer." (PMID 26731558, 2016). "In keeping with the experimental data, and as an example, tenascin C was shown to be expressed in vivo and to colocalize with microvessels in the stroma of non-small cell lung cancer." (PMID 18447899, 2008).
astrocytomas (7 papers, 2007 to 2021). "Tenascin-C, and Aquaporin-1 were significantly upregulated in astrocytoma tissues compared with NAT samples, while HAPLN4 and PPP2R2C were significantly downregulated." (PMID 26252651, 2015). "Among the mRNAs with the raw gProcessed Signal > 500, two of the 5 most upregulated mRNAs (Tenascin-C, Aquaporin-1) and two of the 5 most downregulated mRNAs (HAPLN4, PPP2R2C) were validated in the training set (40 astrocytomas and 20 NAT samples)." (PMID 26252651, 2015). "Also in astrocytomas, TNC is upregulated specifically in ECs and not in tumor cells and its expression level correlates with angiogenic markers." (PMID 33287867, 2020). "In particular, the large TNC variant, containing the FNIII C domain, is mainly expressed around vessels in high grade astrocytoma but it is not present in normal tissues, suggesting that it could represent a therapeutic marker for this kind of tumor." (PMID 33287867, 2020).
breast tumor (7 papers, 2016 to 2024). "TNC is found to support stem cell functions and plays a role in metastasis as the expression of TNC in breast tumor is linked to a higher propensity towards lung metastasis." (PMID 27486983, 2016). "Although tenascin-C appears to have a prominent role in breast tumor invasion and metastasis, we sought to determine whether the loss of cav-1 promoted increased mammary gland expression of tenascin-C." (PMID 28187162, 2017). "We analyzed RNAseq data generated from orthotopic syngeneic engraftment of NT193 breast tumor cells in which TNC expression is high (TNC+) or has been knocked down (TNC−)." (PMID 37176074, 2023). "In addition to fibronectin and collagen, we also investigated the expression of tenascin-C, a matrix protein shown to support breast tumor invasion and lung metastatic niche formation." (PMID 28187162, 2017).
hearing loss (7 papers, 2013 to 2025). "Recently, a novel splice-altering mutation (c.5247A > T, p.Gly1749Gly) in the TNC gene was identified as responsible for autosomal dominant non-syndromic hearing loss in a five-generation Chinese family." (PMID 40203778, 2025). "Herein, we present a case report of a novel mutation in the tenascin-C (TNC) gene in Chinese patients with nonsyndromic hearing loss (NSHL)." (PMID 38640279, 2024). "This study aims to analyze the pathogenic gene in a Chinese family with non-syndromic hearing loss and identify a novel mutation site in the TNC gene." (PMID 39020321, 2024). "Since 2013, TNC has been identified as a novel pathogenic gene associated with non-syndromic hearing loss." (PMID 39020321, 2024). "In this study, a novel splice-altering variant (c.5247A > T, p.Gly1749Gly) in the TNC was identified in a Chinese family with non-syndromic hearing loss." (PMID 39020321, 2024). "This novel splice-altering variant (c.5247A > T, p.Gly1749Gly) in exon 18 of the TNC gene disrupts normal gene splicing and causes hearing loss among HBD families." (PMID 39020321, 2024). "Since the discovery in 2013 that TNC mutation is implicated in non-syndromic hearing loss, TNC has been included in the non-syndromic hearing loss gene database." (PMID 39020321, 2024). "Then using mass spectrum (Sequenom, Inc.)to rank the eight sites, we found only the TNC gene be co-segregated with hearing loss in 53 subjects of F013." (PMID 23936043, 2013). "This represents the first reported instance of a pathogenic splice-altering mutation in the TNC within a non-syndromic hearing loss population, thereby broadening the range of pathogenic loci associated with the genetic database for non-syndromic hearing loss." (PMID 39020321, 2024). "These high priority genes, including MPHOSPH8, MYO18A, TRIOBP, OTOGL, TNC, and MYO6, were previously implicated in hearing loss, balance, and cochlear function, and were significantly enriched in common variant studies of hearing loss." (PMID 38943082, 2024). "A missense mutation c.5317G>A (p.V1773M) in exon 19 of the TNC gene was recently reported as a causative gene for nonsyndromic hearing loss in family-based exome sequencing and linkage analyses." (PMID 25768348, 2015). "Six years later after gene mapped, we successfully identified a novel causative gene for this type of hearing loss in family F013, TNC (Tenascin-C, NC_000009.11, NM_002160.2, NP_002151.2), applying the combined strategy of linkage analysis and whole-exome sequencing." (PMID 23936043, 2013).
lung disease (7 papers, 2011 to 2025). "The expression pattern in the lung of proteins encoded by these genes, fibronectin and tenascin-C, was reported to be related to lung disease." (PMID 29166920, 2017). "Tenascin C (TNC) is an extracellular matrix protein involved in numerous cellular processes in development and can be increased in disease; however, its role in lung diseases is less advanced." (PMID 36829478, 2023). "For example, TNC (Tenascin-C) is associated with lung disease but not specifically with TB34." (PMID 40683862, 2025). "Therefore, targeting TNC may provide a novel therapeutic target for lung diseases." (PMID 36829478, 2023). "The extracellular matrix (ECM) is a diverse group of proteins and glycoproteins, including tenascin C (TNC), collagen, elastin, fibronectin, and proteoglycans, and increased ECM proteins are known to play important roles in the pathogenesis of lung diseases." (PMID 36829478, 2023). "Some of these increased ECM proteins, such as TNC and VCAN, had been involved in tissue remodeling and, specifically, in different lung diseases that imply an altered wound healing." (PMID 25064447, 2014). "Together, these results indicate that even if TNC is no more expressed in adult tissues, its inactivation in early stages persistently affects the lung in adults, in a way that could be relevant for pulmonary diseases with increased airway smooth muscle layer." (PMID 32198404, 2020).
oral squamous cell carcinoma (7 papers, 2016 to 2026). "Recent studies have shown the beneficial effects of targeting TnC in antitumor immunotherapy in breast and oral squamous cell carcinoma mouse models." (PMID 33981316, 2021). "Moreover, tenascin-C was recently shown to contribute to immune suppression in an oral squamous cell carcinoma model." (PMID 33692777, 2020).
osteosarcoma (7 papers, 2015 to 2025). A usually aggressive malignant bone-forming mesenchymal neoplasm, predominantly affecting adolescents and young adults. "In the case of module 3 genes associated with osteosarcoma, eight are found in COSMIC (LUM, COL6A3, TNC, CALU, COL16A1, OMD, ITGB5, and DPSYL3), and two (CDH11 and OMD) are oncogenes found in OncoKB." (PMID 34570764, 2021). "In addition, Scl1 mediates GAS attachment and biofilm formation on ECM deposited by cancer‐associated fibroblasts and osteosarcoma cells that contain cFn isoforms with EDA and/or EDB, and TnC." (PMID 31145503, 2019). "TNC, LUM, COL12A1, COL6A3, and BGN are among the DEPs that differentiate the chondroblastic group from other subtypes of osteosarcoma." (PMID 37681913, 2023). "And LYN, TNC, TGFB2, IGFBP1were up-regulated in the osteosarcoma tissue samples, while IGFBP4, TAGLN, SERPINE1, ANPEP were down-regulated." (PMID 35665757, 2022). "However, the relative expression levels of LYN, TNC, TGFB2, and IGFBP1 were significantly higher in the osteosarcoma group compared with the normal group (P < 0.05)." (PMID 35665757, 2022). "The fact that COL6A3, COL5A2, TNC, and ITGB5 which are highly activated here and part of the focal adhesion-PI3K-Akt signaling axis implies that they are central to osteosarcoma and not simply tissue specific activation." (PMID 34570764, 2021).
Sepsis (7 papers, 2015 to 2024). Sepsis is defined as life-threatening organ dysfunction caused by a dysregulated host response to infection. "To this end, we performed in vivo experiments causing pneumonia and sepsis in TNC−/− and TNC+/+ mice by infection with K. pneumoniae via the airways." (PMID 33776992, 2021). "Further, high expression of tenascin-C was observed in lung tissue of a porcine sepsis model, and was associated with pulmonary inflammation." (PMID 30442110, 2018). "Serum tenascin-C is also associated with prognosis in patients with sepsis: serum tenascin-C levels are an independent prognostic factor, and patients with tenascin-C ≥ 56.9 pg/mL have a significantly increased 30-day mortality." (PMID 30442110, 2018). "In a mouse sepsis model, LPS treatment enhanced the expression of tenascin-C by macrophages, and was associated with induced proinflammatory cytokines by LPS." (PMID 30442110, 2018). "In this study, we conducted a preliminary clinical study to investigate the association between serum tenascin-C concentration and clinical severity, mortality, and inflammatory response in patients with sepsis." (PMID 30442110, 2018). "This study was designed to investigate the relationship between serum tenascin-C levels and disease severity and prognosis in patients with sepsis." (PMID 30442110, 2018). "We also found that serum levels of tenascin-C were significantly positively correlated with several indicators of sepsis, SOFA scores, and serum creatinine." (PMID 30442110, 2018). "We used Logistic multivariate regression model to investigate the independent contribution of tenascin-C to the prognosis of patients with sepsis." (PMID 30442110, 2018). "Serum tenascin-C levels were significantly elevated in patients with sepsis compared with non-sepsis controls (P < 0.001)." (PMID 30442110, 2018). "This study only suggests the association between tenascin-C and damage of extracellular matrix (ECM) in sepsis." (PMID 30442110, 2018). "This article is the first study to investigate the correlation between serum tenascin-C and clinical severity, inflammatory response and prognosis of sepsis." (PMID 30442110, 2018). "We further plotted Kaplan-Meier curve to analyze the effect of high serum tenascin-C on the prognosis of patients with sepsis." (PMID 30442110, 2018). "In all patients with sepsis, serum tenascin-C was significantly positively correlated with SOFA score (P = 0.011), serum creatinine (P = 0.006), CRP (P = 0.001), IL-6 (P < 0.001) and TNF-α (P = 0.026)." (PMID 30442110, 2018). "Our study showed that serum levels of tenascin-C in patients with sepsis were significantly positively correlated with serum inflammatory factors, CRP, IL-6 and TNF-α." (PMID 30442110, 2018). "Our study will provide serum tenascin-C levels as prognostic markers for patients with sepsis." (PMID 30442110, 2018). "In patients with sepsis, serum tenascin-C levels were significantly positively correlated with SOFA scores (P = 0.011), serum creatinine (P = 0.006), C-reactive protein (CRP) (P = 0.001), interleukin-6 (IL-6) (P < 0.001), and tumor necrosis factor α (TNF-α) (P = 0.026)." (PMID 30442110, 2018). "This suggests that tenascin-C may be involved in the pathogenesis of sepsis and become a potential therapeutic target." (PMID 30442110, 2018). "Our results suggest that tenascin-C may be involved in the pathogenesis of sepsis and serve as a potential biomarker and therapeutic target." (PMID 30442110, 2018). "We hypothesize that in sepsis, LPS drives expression of tenascin-C in injured tissues including ECM, which is released into circulation." (PMID 30442110, 2018). "Our research indicates that tenascin-C is a protein with multiple biological functions, and may be involved in the pathogenesis of sepsis through numerous unknown mechanisms." (PMID 30442110, 2018). "This suggests that tenascin-C may be an inflammation promoting factor for sepsis and its expression may be increased in various tissues." (PMID 30442110, 2018).
Sepsis (continued). "Our study found that serum levels of tenascin-C in septic patients were significantly higher than non-sepsis controls, indicating that tenascin-C may be a serum molecular biomarker of sepsis." (PMID 30442110, 2018). "To determine the role of TNC in the host response during Klebsiella pneumonia derived sepsis we assessed bacterial burdens at the primary site of infection (lungs) and distant body sites (blood, liver and spleen) in TNC+/+ and TNC−/− mice 24 and 42 h after infection." (PMID 33776992, 2021). "While this investigation is limited to a single model and a single causative pathogen, and the absence of TNC could be compensated through different pathways, the results reported here argue against an important role for total TNC protein as a driver in the early pathogenesis of sepsis." (PMID 33776992, 2021). "Serum tenascin-C levels (median 56.7 pg/mL) were significantly higher in septic patients than in controls (critically ill patients without sepsis) (median 24.1 pg/mL) (P < 0.001)." (PMID 30442110, 2018). "In patients with sepsis, serum levels of tenascin-C were significantly higher in the nonsurvivors (median 64.9 pg/mL) compared with survivors (median 53.3 pg/mL) (P < 0.001)." (PMID 30442110, 2018). "In this study, we measured serum tenascin-C levels in 167 patients with sepsis and 80 controls from critically ill patients without sepsis." (PMID 30442110, 2018). "To date, no studies have reported change of serum tenascin-C levels in sepsis and whether it could reflect disease activity and prognosis." (PMID 30442110, 2018).
systemic sclerosis (7 papers, 2021 to 2025). A chronic disorder, possibly autoimmune, marked by excessive production of collagen which results in hardening and thickening of body tissues. "Tenascin C was recently shown to be highly upregulated in systemic sclerosis and to be associated with fibrosis, while SH3PXD2A (formerly TKS5) is involved in extracellular matrix degradation in both normal podosomes/invadopodia and in cancer cells." (PMID 39112965, 2024). "We have previously demonstrated that DAMPs such as fibronectin-EDA (Fn-EDA) and tenascin-C are markedly upregulated in skin and lungs, and are markers of tissue fibrosis, in patients with systemic sclerosis (SSc)." (PMID 36136452, 2022). "More recently, TNC was identified as one of ten hub differentially expressed genes in skin that could sensitively and specifically distinguish systemic sclerosis from healthy controls." (PMID 36404995, 2022). "However, systemic sclerosis fibroblasts did highly upregulate expression of POSTN, TNC, and TIMP1." (PMID 39989459, 2025). "Fibronectin-EDA and tenascin-C may activate Toll receptor 4 (TLR4) and lead to uncontrolled extracellular matrix (ECM) deposition in systemic sclerosis (SSc), which subsequently enhances transforming growth factor beta (TGF-β) signaling, thus promoting fibrotic responses." (PMID 40843700, 2025).
brain cancer (6 papers, 2011 to 2024). A primary or metastatic malignant neoplasm affecting the brain. "Localized TNC expression has previously been shown to associate with disease activity; elevated levels of TNC in the tumour stroma correlate with metastasis and poor prognosis in both breast and brain cancer." (PMID 23193984, 2012). "Furthermore, PL1, a 12-amino acid peptide simultaneously targeting both EDB-FN and tenascin-C, has recently been developed to deliver iron oxide nanoworms to brain cancers." (PMID 36899821, 2023). "Tenascin-C, an extracellular protein majorly expressed during embryonic development is known to disappear in adults but reappears at the site of wound healing in cases of brain cancer and colorectal carcinoma." (PMID 28469129, 2017).
hepatocellular carcinoma (6 papers, 2016 to 2025). A malignant tumor that arises from hepatocytes. "For example, TNF-α can promote the expression of tenascin-C in hepatoma cells and promote metastasis of cancer cells." (PMID 30442110, 2018). "A higher level of Tenascin-C expression was found in patients with metastatic hepatocellular carcinoma (HCC), and overexpression of Tenascin-C was highly correlated with poor prognosis in HCC patients." (PMID 26731558, 2016). "Co-treatment with KPA also decreased the expression of genes, regulating the progression of fibrosis (e.g., COL6A3, AEBP1, SPARC, TNC, LAMB1, BGN) and hepatocellular carcinoma (e.g., COL4A1, COL4A2, TUFT1, VCAN, NID1)." (PMID 39404414, 2024).